KDM5A (lysine demethylase 5A)
Diseases named in the same sentence as KDM5A in open-access papers (continued):
Sharing a sentence is not in itself a finding about the gene and the disease.
alopecia areata (1 paper, 2024). Loss of scalp and body hair involving microscopically inflammatory patchy areas. "It shows that alopecia areata increased KDM5A, MLL, SETD7, and G9A expression, as well as reduced LSD1, KDM4A, and KDM4B expression." (PMID 39046182, 2024). "In line with our results, a previous study found the opposite trend of LSD1 and KDM5A in patients with alopecia areata." (PMID 39046182, 2024).
Anxiety (1 paper, 2020). Intense feelings of nervousness, tension, or panic often arise in response to interpersonal stresses. "Additional behavioral characterization is required to thoroughly assess anxiety in the Kdm5a-/- mice." (PMID 33350388, 2020). "In addition, we found that the Kdm5a-/- mice spent significantly less time in the center of the arena indicating a possible anxiety phenotype." (PMID 33350388, 2020). "Kdm5a-/- mice also had mild hyperactivity and showed signs of anxiety in the open field test." (PMID 33350388, 2020).
breast adenocarcinoma (1 paper, 2011). "We continued using KDM5A dataset from U937 cells but used H3K4me3 dataset from breast adenocarcinoma MCF7 cells." (PMID 21886846, 2011).
chronic hepatitis B (1 paper, 2024). "For instance, several KDM5A inhibitors have demonstrated promising outcomes in anti-cancer, and there is also a KDM5A inhibitor, GS-5801, which has entered phase 1 clinical trials for chronic hepatitis B." (PMID 39716081, 2024).
cognitive decline (1 paper, 2022). "Additionally, we find that mitochondrial damage affects the proteostasis of the epigenetic regulator lysine demethylase 5A (KDM5A), resulting in dysregulation of AHN and cognitive decline." (PMID 36056186, 2022).
cryptorchidism (1 paper, 2023). The failure of one or both testes of a male fetus to descend from the abdomen into the scrotum during the late part of pregnancy. "In artificially induced cryptorchidism, Kdm5a overexpression led to increased stimulation of five testicular development genes." (PMID 37730534, 2023).
depression (1 paper, 2021). "We detected high impact variants in genes previously implicated in depression (e.g. Gnat2), depression-like behavior (e.g. Prlr, Nlrp1a), other psychiatric disease (e.g. Pou6f2, Kdm5a, Reep3, Wdfy3), and responses to psychological stressors (e.g. Pigr)." (PMID 34285244, 2021).
Ewing sarcoma (1 paper, 2020). A small round cell tumor that lacks morphologic, immunohistochemical, and electron microscopic evidence of neuroectodermal differentiation. "Our studies provide evidence that, in Ewing sarcoma, KDM5A activates expression of L1CAM (and MCAM) via a demethylase-independent mechanism." (PMID 33196691, 2020). "Examination of regulatory control of MCAM in different Ewing sarcoma cell lines revealed positive regulation by KDM5A in both A673 and SK-ES-1 cells, and by PHF2 in A673 cells." (PMID 33196691, 2020). "Together, these data indicate that KDM5A and PHF2 each promote growth and metastatic properties in Ewing sarcoma." (PMID 33196691, 2020). "To probe the functional roles of KDM5A and PHF2 in Ewing sarcoma, we stably depleted each factor in patient-derived Ewing sarcoma cell lines, using lentivirally delivered shRNAs." (PMID 33196691, 2020). "Here, we show that the epigenetic regulators KDM5A and PHF2 promote growth and metastatic properties in Ewing sarcoma, and, strikingly, activate expression many pro-metastatic genes repressed by EWS/Fli1." (PMID 33196691, 2020). "In the present study, we present evidence that epigenetic mechanisms, involving the chromatin factors KDM5A and PHF2, importantly contribute to Ewing sarcoma progression, in part through their opposing effects on EWS/Fli1-controlled gene expression." (PMID 33196691, 2020). "Together, these studies identify KDM5A and PHF2 as novel disease-promoting factors, and potential new targets, in Ewing sarcoma, including the more metastatically potent EWS/Fli1low cell population." (PMID 33196691, 2020). "Treatment of Ewing sarcoma A673 cells with CPI-455 resulted in increased levels of H3K4me3, similar to KDM5A depletion." (PMID 33196691, 2020). "Together, these data suggested that KDM5A and PHF2 could be novel disease-promoting factors in Ewing sarcoma." (PMID 33196691, 2020). "Stable depletion of KDM5A and PHF2 each resulted in inhibition of colony formation, indicating that both factors exert growth-promoting effects in Ewing sarcoma." (PMID 33196691, 2020). "Our studies further identify a group of genes previously implicated in metastasis, whose opposing regulatory control by KDM5A/PHF2 and EWS/Fli1 may importantly contribute to modulation of Ewing sarcoma metastatic potency." (PMID 33196691, 2020). "Seeking to further understand the biology of JHDMs in Ewing sarcoma, we noted the JHDMs KDM5A (JARID1A/RBBP2) and PHF2 (KDM7C/JHDM1E) to be consistently upregulated in expression in patient-derived Ewing sarcoma cell lines, relative to mesenchymal stem cells, the putative disease cell of origin." (PMID 33196691, 2020). "To obtain further insight into mechanisms by which KDM5A and PHF2 function as disease promoting factors in Ewing sarcoma, we defined their respective transcriptomes using RNAseq, comparing gene expression in A673 Ewing sarcoma cells stably depleted of each factor and shRNA control cells." (PMID 33196691, 2020). "Inspection of individual genes of interest revealed that KDM5A and PHF2 each positively control the expression of Ets1 and MCAM, genes belonging to a metastasis-promoting pathway recently identified in Ewing sarcoma by our group, and negatively regulated by EWS/Fli1." (PMID 33196691, 2020). "Having shown that KDM5A and PHF2 promote metastatic properties in Ewing sarcoma, and exert effects on metastasis in opposition to those of EWS/Fli1, we wondered whether inhibition of KDM5A or/and PHF2 could impair the biological properties of more metastatically potent EWS/Fli1low cells." (PMID 33196691, 2020).
folate deficiency (1 paper, 2025). A nutritional condition produced by a deficiency of FOLIC ACID in the diet. "To investigate the mechanism underlying the downregulation of KDM5A transcription under conditions of folate deficiency, we screened for candidate transcription factor (TF)-binding motifs near the KDM5A promoter." (PMID 41266313, 2025). "Our study identifying a novel epigenetic pathway wherein folate deficiency caues NTDs through the transcriptional silencing of the histone demethylase KDM5A, leading to H3K4me3-mediated hyperactivation of wnt/β-catenin signalling." (PMID 41266313, 2025).
hearing loss (1 paper, 2022). "Our findings have broad significance and call for the transformation of KDM5A as a potential therapeutic target for the treatment of hearing loss in the future." (PMID 36396833, 2022). "Altogether, our findings indicate that inhibition of KDM5A may represent an effective epigenetic therapeutic target for preventing cisplatin-induced hearing loss." (PMID 36396833, 2022). "The present study showed that KDM5A participates in CP-induced hearing loss." (PMID 36396833, 2022). "Here, we demonstrated that inhibiting KDM5A activity with CPI-455 reduces mitochondrial apoptosis, thus broadening our understanding of epigenetic modifications as novel targets to prevent CP-induced hearing loss." (PMID 36396833, 2022).
heart failure (1 paper, 2022). Inability of the heart to pump blood at an adequate rate to meet tissue metabolic requirements. "Moreover, KDM5A is associated with heart failure, congenital heart disease, and arrhythmogenic right ventricular cardiomyopathy." (PMID 35845066, 2022). "Many studies have shown that KDM5A plays an important role in epigenetic modifications during the development of heart failure." (PMID 35845066, 2022).
Hodgkins lymphoma (1 paper, 2018). A heterogeneous group of malignant lymphoid neoplasms of B-cell origin characterized histologically by the presence of Hodgkin and Reed-Sternberg (HRS) cells in the vast majority of cases.
lentivirus infection (1 paper, 2025). Virus diseases caused by the Lentivirus genus. "For the KDM5A lentivirus infection, the lentiviral vectors were transfected into 293 T cells with the sh-NC and sh-KDM5A packaging plasmid mix in serum-free Opti-MEM using the lipofectamine 3000 reagent with multiplicity of infection (MOI) of 20 and with or without 5 μg/ml polybrene." (PMID 41266313, 2025).
malignant glioma (1 paper, 2018). A grade III or grade IV glioma arising from the central nervous system. "Several histone demethylases, including LSD1, KDM5A, and KDM5B, are upregulated in malignant gliomas, sustaining cell growth, and resistance to chemotherapy." (PMID 29360266, 2018).
metastatic disease (1 paper, 2020). "Strikingly, animals with KDM5A-depleted cells showed a dramatic reduction in metastatic disease burden (top)." (PMID 33196691, 2020). "Similar to our findings in the orthotopic model, stable depletion of KDM5A and PHF2 each resulted in a robust decrease in metastatic disease burden in this model." (PMID 33196691, 2020).
neuroblastoma (1 paper, 2017). Neuroblastoma (NB) is the most common solid, extracranial childhood tumor. "Interestingly, several sequence alterations in other genes involved in chromatin regulation in neuroblastoma have been found, including EP300, CREBBP, TTF2, KDM5A, CHD9, and gene IKZF1, which might undergo somatic mutations and promote NB occurrence." (PMID 28055978, 2017).
Obesity (1 paper, 2025). Accumulation of substantial excess body fat. "These suggest that low activity of KDM5A is linked with enhanced myeloid output in response to tissue injury in the HFD-induced obesity environment." (PMID 40795290, 2025). "We next determined whether KDM5A-KO further enhances its myelopoietic phenotype in response to HFD-induced obesity." (PMID 40795290, 2025). "KDM5A-KO was not sufficient to further increase myelopoietic phenotype induced by HFD-induced obesity." (PMID 40795290, 2025).
primary immunodeficiencies (1 paper, 2018). "WES revealed heterogeneous genetic background among CVID patients with tumors, identifying gene variants associated with primary immunodeficiencies (such as CTLA4, PIK3CD, PMS2) and/or increased cancer susceptibility (including BRCA1, RABEP1, EP300, KDM5A)." (PMID 30723478, 2018).
renal fibrosis (1 paper, 2024). A final common manifestation of a wide variety of chronic kidney diseases characterized by glomerulosclerosis and tubulointerstitial fibrosis. "KDM5A is a negative regulator of histone H3K4 trimethylation, while TGF-β1 induces kidney aging through H3K4me3, ultimately resulting in renal fibrosis and inflammation." (PMID 39716081, 2024).
thyroid cancer (1 paper, 2022). "Intriguingly, we found that several histone demethylases such as KDM5B, KDM1A, KDM6B, KDM5A and KDM1B, were enriched in thyroid cancer spheres compared to non-CSCs." (PMID 35198054, 2022).
cancer (105 papers, 2010 to 2025). A tumor composed of atypical neoplastic, often pleomorphic cells that invade other tissues. "KDM5A, in addition to regulating several cellular processes such as differentiation and cell cycle progression, has been linked to various cancer phenotypes." (PMID 40545232, 2025). "According to previous studies, KDM5A/B/C are associated with BC, either in pro-tumorigenic or anti-cancer roles." (PMID 38769556, 2024). "In RB-deficient SCLC, KDM5A activity was shown to be required for the maintenance of the neuroendocrine phenotype and to promote cancer cell proliferation." (PMID 35899196, 2022). "KDM5A is associated with cancer growth, differentiation, multi-drug resistance, invasion, and metastasis in various cancers." (PMID 33596982, 2021). "KDM5A is associated with many non-cancer diseases, such as congenital heart disease (CHD) and bacterial, viral, or parasitic infection." (PMID 33596982, 2021). "In the present study, we investigated the cancer-promoting mechanism of KDM5A underlying the pathogenesis of PCa." (PMID 33087165, 2020). "L1CAM, another cell surface protein strongly implicated in cancer progression and metastasis, demonstrated positive regulatory control by KDM5A and PHF2 in both cell lines." (PMID 33196691, 2020). "KDM5A is linked with multiple human cancer types, including tumors of the breast, lung, prostate, and stomach." (PMID 30650517, 2019). "KDM5A regulates the control of cell division and differentiation and is associated with inferior prognosis in different cancers." (PMID 30650517, 2019). "One particular gene that encodes the histone lysine demethylase KDM5A is overexpressed in several cancers." (PMID 35582714, 2019). "KDM5A has been implicated in cancer processes including cell proliferation, metastasis and drug resistance." (PMID 27224921, 2016). "For example, the emergence of drug-tolerant persisters in cancer cell lines treated with various anti-cancer agents involved alteration of H3K4 demethylation linked to the demethylase Kdm5a." (PMID 23520493, 2013). "For example, a census of frequently mutated cancer genes identified KDM5A, 5C and 6A are implicated in several malignancies, including acute myeloid leukemia, esophageal, renal and squamous cell carcinomas." (PMID 22867098, 2012). "The protein encoded by KDM5A, a retinoblastoma tumor suppressor (Rb)-binding lysine-specific histone demethylase, has been recently implicated in cancer drug tolerance." (PMID 22291905, 2012). "Interestingly, overexpression of KDM5A or KDM5B is also implicated in several cancers progression and drug resistance." (PMID 37034668, 2023). "The knockdown of KDM5A resulted in the loss of clonogenic potential, cell cycle arrest at the G1 phase, and increased levels of cyclin-dependent kinase inhibitors p21 and p27 in a variety of cancer cell lines." (PMID 35326475, 2022). "In both cancer and developmental contexts, phenotypes caused by RB dysfunction could be rescued by inhibiting KDM5A, leading to the hypothesis that at least part of the functional link between RB and KDM5A may be based on antagonizing roles." (PMID 35899196, 2022). "KDM5A is increased in drug-resistant cancer cell populations and its association with HDACs may underlie cell sensitivity to the HDAC inhibitors TSA and SAHA." (PMID 21886846, 2011). "Therefore, overexpression of KDM5A is assumed to reduce H3K4me2/3 level in the promoter genes involved in the genes responsible for differentiation and aging, as well as the inhibitory genes that cause cancer." (PMID 37107631, 2023). "The role of KDM5A in cancer is continuing to be elucidated, but overexpression is thought to drive progression." (PMID 40160429, 2025).
cancer (continued). "KDM5A thus presents an attractive anti-cancer target due to its role in the progression of a wide variety of cancers." (PMID 40545232, 2025). "In the context of cancer, there is compelling evidence of direct interactions and close interplay of KDM5A and KDMB with the Retinoblastoma protein RB, and both catalytic and not-catalytic KDM5 functions are involved in this cross-talk." (PMID 39000010, 2024). "KDM5A/B appear to play several roles in tumorigenesis, including promoting cell cycle progression and regulating the metabolism of cancer stem cells." (PMID 36803422, 2023). "The high mutation rates of epigenetic regulators such as H3F3A, KDM5A, and EP300 suggest a unique etiologic aspect of AYA cancers that remains poorly understood." (PMID 36433963, 2022). "Vinogradova and collaborators demonstrated that treating cancer cells with a specific inhibitor of the histone demethylase KDM5A results in the ablation of a subpopulation of founder cancer cells in multiple tumor cell line models." (PMID 35158815, 2022). "One observation was a marked transcriptional heterogeneity of cancer cells depending on KDM5A and B functions." (PMID 35899196, 2022). "As an effector mediated by the PI3K/AKT signaling pathway, lysine-specific demethylase 5A (KDM5A) is responsible for driving multiple human diseases, particularly cancers." (PMID 35845066, 2022). "RNA-sequencing data for cancer cells depleted of KDM5A or KDM5B demonstrate the heterogeneity of their target genes." (PMID 36509829, 2022). "Elevated expression of KDM5A/B has been detected in a small subpopulation of slowly proliferating, tumor-initiating cells that show intrinsic resistance to a wide variety of cancer therapeutics, including cytotoxic and targeted agents." (PMID 35326475, 2022). "In cancer treatment, KDM5A-specific inhibitors can reduce the drug resistance of cancer cells and induce tumor cell death." (PMID 36396833, 2022). "Increased levels of KDM5A and KDM5B have been associated with chemoresistance in cancer and appear to contribute to an increase in cancer cell proliferation." (PMID 35563709, 2022). "Lysine-specific demethylase 5A (KDM5A) which is participated in human cancer has been inhibited through binding of NEAT1 to the E2F transcription factor 1 (E2F1) protein." (PMID 35676702, 2022). "We benchmark SAPT(VQE) (with the VQE component simulated by ideal statevector simulators) against a handful of small multi-reference dimer systems and the iron center containing human cancer-relevant protein lysine-specific demethylase 5 (KDM5A)." (PMID 35414867, 2022). "KDM5A was further identified as a critical factor characterizing drug tolerant persister cancer cells that mediated intrinsic resistance towards chemotherapy in a non-small cell lung cancer (SCLC) cell line." (PMID 35899196, 2022). "The silencing of KDM5A increased the expression of CDH1 and reduced the expression of Vimentin, suggesting that KDM5A regulates the expression of mesenchymal markers in persister cancer cells." (PMID 35326475, 2022). "Increasing evidence suggests that KDM5A plays an oncogenic role in tumorigenesis and the progression of human cancer." (PMID 33578894, 2021). "KDM5A is overexpressed in several cancers including acute myeloid leukemia and lung cancers, KDM5B in breast cancer and melanoma, and KDM5C in prostate cancers, as well as metastatic breast and gastric cancers." (PMID 34184733, 2021). "KDM5A was well known in many types of human cancer pathogenesis via promotion of cell growth, inhibition of tumor suppressor gene expression, and development of drug tolerance." (PMID 33436536, 2021). "In myeloid malignancies KDM5A and KDM5B show enzymatic activity towards H3K4me3 while little is known about KDM5C and KDM5D in this context." (PMID 34944554, 2021).